WDR74 (WD repeat domain 74)
Description:
Regulatory protein of the MTREX-exosome complex involved in the synthesis of the 60S ribosomal subunit. Participates in an early cleavage of the pre-rRNA processing pathway in cooperation with NVL. Required for blastocyst formation, is necessary for RNA transcription, processing and/or stability during preimplantation development (By similarity).
Synonyms: NSA1; FLJ10439
Tractability: Small molecule: a structure with a bound ligand is known. PROTAC: ubiquitination databases record sites on it; its protein half-life has been measured.
Gene: Protein-coding gene on chromosome 11 (62,832,342 to 62,842,228, reverse strand). Ensembl gene ENSG00000133316.
Subcellular location: Nucleus, nucleolus; Nucleus
Subcellular location (Human Protein Atlas): Nucleoli; Nucleoplasm
Gene Ontology:
Molecular function: protein binding
Biological process: ribosomal large subunit biogenesis; rRNA processing; blastocyst formation; RNA metabolic process
Cellular component: nuclear exosome (RNase complex); nucleolus; nucleus; preribosome, large subunit precursor
Genetic constraint (gnomAD): Loss-of-function variants: 31 observed, 47.07 expected, observed/expected ratio (o/e) 0.66, 90% interval 0.49 to 0.89. The upper end of that interval is the gene's LOEUF score, 0.89, which puts it in group 3 of 6, group 1 being the genes least tolerant of losing a copy. Missense variants: 455 observed, 504.44 expected, observed/expected ratio (o/e) 0.9, 90% interval 0.83 to 0.98. Synonymous variants: 191 observed, 198.76 expected, observed/expected ratio (o/e) 0.96, 90% interval 0.85 to 1.08.
Homologues: Orthologues: chimpanzee WDR74 (99% identical), macaque WDR74 (98% identical), pig WDR74 (91% identical), rabbit WDR74 (90% identical), dog WDR74 (90% identical), mouse Wdr74 (89% identical), rat Tex54 (87% identical), guinea pig WDR74 (82% identical), tropical clawed frog wdr74 (50% identical), zebrafish wdr74 (49% identical), Caenorhabditis elegans T06E6.1 (32% identical), Drosophila melanogaster l(2)k09848 (29% identical).
Diseases named in the same sentence as WDR74 in open-access papers:
WDR74 is named in the same sentence as 30 diseases in open-access papers, as found by Europe PMC text mining. Sharing a sentence is not in itself a finding about the gene and the disease. The quoted sentences say what the papers report.
lung carcinoma (4 papers, 2021 to 2025). "In summary, WDR74 expression level was significantly associated with the poor prognosis in several cancers, especially in lung cancer, ACC, and PRAD." (PMID 35559034, 2022). "Mutation analysis demonstrated that WDR74 is frequently mutated in promoter regions of lung cancer and has the R181L/Q hotspot mutation in skin cutaneous melanoma and glioblastoma." (PMID 35559034, 2022). "WDR74 has been shown to be a novel Smad-binding protein associated with the pathogenesis of lung cancer." (PMID 34553072, 2021). "Mutation analysis demonstrated that WDR74 is frequently mutated in promoter regions of lung cancer." (PMID 35559034, 2022). "The pooling analysis results in the Oncomine database further demonstrated that WDR74 is highly expressed in brain and CNS cancer, breast cancer, colorectal cancer, lung cancer, or lymphoma compared with normal controls." (PMID 35559034, 2022). "Furthermore, we utilized the Kaplan–Meier plotter tool to obtain the correlation between WDR74 expression and prognosis in breast cancer, lung cancer, gastric cancer, ovarian cancer, and liver cancer." (PMID 35559034, 2022). "In addition, WDR74 promoted the proliferation and migration of lung cancer by inducing the nuclear translocation of β-catenin and activating the Wnt signaling pathway." (PMID 34553072, 2021). "WDR74 has been reported to be upregulated in various cancers, including HCC 42, colorectal cancer 43, lung cancer 44, and melanoma 32, suggesting its role as a tumor-promoting factor." (PMID 40959275, 2025). "Additionally, we found that the high WDR74 expression level predicted the poor OS, FP, and PPS (all p < 0.001) in lung cancer." (PMID 35559034, 2022).
colorectal cancer (3 papers, 2021 to 2025). A primary or metastatic malignant neoplasm that affects the colon or rectum. "Previous researchers claimed that WDR74 promotes proliferation and metastasis in lung and colorectal cancer cells through regulating the Wnt/β-catenin signaling pathway." (PMID 35559034, 2022). "In addition, in vitro studies showed that WDR74 could induce nuclear β-catenin accumulation and activate Wnt responsive genes to promote cancer growth and metastasis in lung and colorectal cancer." (PMID 35559034, 2022).
melanoma (3 papers, 2022 to 2025). A malignant, usually aggressive tumor composed of atypical, neoplastic melanocytes.
acute myeloid leukemia (1 paper, 2022). Acute myeloid leukemia (AML) is a group of neoplasms arising from precursor cells committed to the myeloid cell-line differentiation. "Highly expressed WDR74 was associated with poor prognosis of OS in cancers of ACC (adrenocortical carcinoma) (p < 0.001), LAML (acute myeloid leukemia) (p < 0.01), LIHC (p < 0.05), and PRAD (p < 0.01) from the TCGA project." (PMID 35559034, 2022).
bladder cancer (1 paper, 2023). "Mutations at specific hotspots in non-coding regions of ADGRG6, PLEKHS1, WDR74, TBC1D12 and LEPROTL1 frequently occur in bladder cancer (BC)." (PMID 36658180, 2023).
breast carcinoma (1 paper, 2022). "The analysis results of the CPTAC dataset showed higher expression of WDR74 protein in breast cancer, clear cell RCC, colon cancer, LUAD, ovarian cancer, and UCEC (p < 0.001)." (PMID 35559034, 2022). "We observed that WDR74 expression was negatively correlated with the OS (p < 0.001) and DMFS (p < 0.01) for breast cancer." (PMID 35559034, 2022).
diffuse large B-cell lymphoma (1 paper, 2022). "To explore the expression feature in these tumors, we combined the TCGA and GTEx datasets to get enough normal samples as paired tissues and observed the high-expression WDR74 in DLBC (lymphoid neoplasm diffuse large B-cell lymphoma) and THYM (thymoma) (p < 0.05)." (PMID 35559034, 2022).
gastric cancer (1 paper, 2022). A primary or metastatic malignant neoplasm involving the stomach. "However, a low expression level of WDR74 was associated with poor OS (p < 0.01) and PFS (p < 0.05) in ovarian cancer and poor OS (p = 0.01) and FP (p < 0.05) in gastric cancer." (PMID 35559034, 2022).
lung squamous cell carcinoma (1 paper, 2022). "Our preliminary research demonstrated that WDR74 is over-expressed in lung squamous cell carcinoma (LUSC) and related with worse survival." (PMID 35559034, 2022). "Our preliminary immunohistochemistry (IHC) analysis based on the tissue microarray (TMA) demonstrated higher expression of WDR74 protein in lung squamous cell carcinoma (LUSC) than in normal tissues (paired t-test, p-value < 0.001)." (PMID 35559034, 2022).
neuroblastoma (1 paper, 2026). Neuroblastoma (NB) is the most common solid, extracranial childhood tumor. "Complementary experiments in neuroblastoma cell lines reveal functional roles for TSR3 and WDR74 in mesenchymal-like tumor states." (PMID 41803115, 2026).
Skin Cutaneous Melanoma (1 paper, 2022). "The “Pathological Stage Plot” module of the HEPIA2 database was applied to depict the correlation between WDR74 expression and the pathological stages of cancers, including ESCA, KICH (Kidney Chromophobe), and SKCM (Skin Cutaneous Melanoma) (all p < 0.05)." (PMID 35559034, 2022).
cancer (7 papers, 2018 to 2025). A tumor composed of atypical neoplastic, often pleomorphic cells that invade other tissues. "Previous research reported that the WDR74 promoter is frequently mutated in various cancers (ICGC/TCGA Pan-Cancer Analysis of Whole Genomes Consortium, 2020)." (PMID 35559034, 2022). "WDR74 has been implicated to participate in the metastatic potential of cancer cells." (PMID 34553072, 2021). "Our first pan-cancer study inferred a relatively comprehensive understanding of the oncogenic roles of WDR74 across various cancers." (PMID 35559034, 2022). "Based on a pan-cancer pathway enrichment analysis, we first identified that WDR74 participates in cellular biogenesis of the RNA metabolism and its critical role in cancer initiation and progression through the tumor cell energy metabolism." (PMID 35559034, 2022). "It is worth noting that in DLBC, WDR74 expression increased, but the prognosis was good, which was contrary to other cancers." (PMID 35559034, 2022). "WDR74 is highly expressed in most cancers and correlated with poor prognosis in several cancers (all p < 0.05)." (PMID 35559034, 2022). "We thus investigated the potential oncogenic roles of WDR74 across 33 tumors based on the database of TCGA (The Cancer Genome Atlas) and GEO (Gene Expression Omnibus)." (PMID 35559034, 2022). "We also investigated the potential molecular mechanism of WDR74 in the pathogenesis or clinical prognosis of different cancers by analyzing correlative factors to further confirm its oncogenic role in tumors." (PMID 35559034, 2022). "The GO (Gene Ontology) enrichment analysis of the WDR74 pathway revealed its participation in cellular biogenesis of the RNA metabolism and its critical role in cancer initiation and progression through the tumor cell energy metabolism." (PMID 35559034, 2022). "Our study, for the first time, based on previous results and combined with the TCGA project and GEO databases, conducted a pan-cancer analysis of WDR74 in various tumors." (PMID 35559034, 2022). "Our pan-cancer analysis showed high-level expression of WDR74 in tumor tissues (p < 0.05) and its correlation with poor prognosis in several tumors." (PMID 35559034, 2022). "Moreover, we found that CD8+ T-cells and the fibroblast infiltration level increased in WDR74 over-expressed cancer cells." (PMID 35559034, 2022). "Although several studies have prompted oncogenic roles of WDR74 in tumors, WDR74 is not mentioned as a cancer consensus gene in COSMIC (Catalogue of Somatic Mutations in Cancer)." (PMID 35559034, 2022). "More recently, mutations in the regulatory regions of other cancer-related genes have been identified, including recurrent mutations in the promoters of PLEKHS1, WDR74, SDHD, and FOXA1 that alter gene expression levels, TF binding and that are associated with poor prognosis." (PMID 29456552, 2018). "In this study, we first demonstrated the molecular mechanism of WDR74 in CRC and its interaction with cancer proliferation and metastasis." (PMID 34553072, 2021). "The most frequent cMDT disrupting interactions in over 90% of samples of a cancer type were those from the genes USP46, WDR74, RPS19, BOLA2B, NDUFA9, and LAMA3." (PMID 32879328, 2020). "For instance, we observed significant negative correlation between the WDR74 expression level in SARC and the infiltration level of cancer-associated fibroblasts (cor = −0.419, P < 0.001) utilizing the TIDE algorithm." (PMID 35559034, 2022). "Although emerging patient-derived samples and cellular-based evidence support the relationship between WDR74 (WD Repeat Domain 74) and carcinogenesis in multiple cancers, no systematic pan-cancer analysis is available." (PMID 35559034, 2022). "Moreover, there is still no pan-cancer analysis on the relationship between WDR74 and various tumor types based on data-driven evidence." (PMID 35559034, 2022).
tumor (7 papers, 2021 to 2026). "Protein 74 (WDR74), which consists of the WD repetition sequence, has been previously associated with tumor tumorigenesis." (PMID 34553072, 2021). "WDR74 is implicated in tumorigenesis, especially in tumor growth and metastasis." (PMID 40510136, 2025). "Based on our previous conclusion, WDR74 was highly expressed in multiple tumor tissues and correlated with worse prognosis in several tumors, suggesting its potential oncogenic role in carcinogenesis." (PMID 35559034, 2022). "Tumor microenvironment analysis revealed that ImmuneScore, StromalScore, and EstimateScore were correlated with a low WDR74 expression level in LUSC (R = −0.441, p < 0.001)." (PMID 35559034, 2022). "The results demonstrated that macrophage-IL1B and macro-WDR74 were activated in low tumor cell microenvironment, which promoted the anti-MM immunity." (PMID 36532059, 2022). "Data showed that the expression of WDR74 was increased in 288 CRC tumor tissues when compared with that in 41 normal colorectal tissues." (PMID 34553072, 2021). "Additionally, we sought out top 100 genes that correlated with WDR74 by combing all TCGA tumor data in GEPIA2." (PMID 35559034, 2022). "In addition, WDR74 participates in tumorigenesis through the tumor cell energy metabolism pathway and holds the potential role as a diagnostic biomarker as well as future therapeutic targets in multiple tumors." (PMID 35559034, 2022). "The KEGG analyses suggested that “Ribosome” might be involved in the effect of WDR74 on tumor pathogenesis." (PMID 35559034, 2022). "This suppression was partially reversed by WDR74 overexpression, while SLC7A11 knockdown mitigated the tumor-promoting effects." (PMID 40959275, 2025). "We investigated the oncogenic role of WDR74 in CRC and found a significant increase in WDR74 expression in CRC cells, which was corroborated with the results from the TCGA database in CRC tumor samples." (PMID 34553072, 2021). "Based on the TCGA project, the study evaluated the potential connection between the infiltration level of different immune cells and WDR74 gene expression applying the TIMER, CIBERSORT, QUANTISEQ, TIDE (Tumor Immune Dysfunction and Exclusion), XCELL, MCPCOUNTER, and EPIC algorithms." (PMID 35559034, 2022).
WDR74 also shares sentences with these, for which no sentence is quoted: anorexia nervosa (1 paper); CNS cancer (1); colon cancer (1); COVID-19 (1); depression (1); glioblastoma (1); hepatocellular carcinoma (1); liver cancer (1); lymphoid neoplasm (1); lymphoma (1); osteoarthritis (1); osteosarcoma (1); ovarian carcinoma (1); prostate carcinoma (1); schizophrenia (1); thymoma (1); uterine carcinosarcoma (1).